PGM2L1 (phosphoglucomutase 2 like 1)
Description:
Glucose 1,6-bisphosphate synthase using 1,3-bisphosphoglycerate as a phosphate donor and a series of 1-phosphate sugars, including glucose 1-phosphate, mannose 1-phosphate, ribose 1-phosphate and deoxyribose 1-phosphate, as acceptors. In vitro, also exhibits very low phosphopentomutase and phosphoglucomutase activity which are most probably not physiologically relevant.
Synonyms: BM32A; FLJ32029; NEDHFS; PMMLP
Tractability: PROTAC: ubiquitination databases record sites on it; its protein half-life has been measured.
Gene: Protein-coding gene on chromosome 11 (74,330,315 to 74,398,473, reverse strand). Ensembl gene ENSG00000165434.
Subcellular location: Cytoplasm, cytosol
Subcellular location (Human Protein Atlas): Mitochondria
Pathways (Reactome):
Metabolism: Glycolysis
Gene Ontology:
Molecular function: glucose-1,6-bisphosphate synthase activity; phosphoglucomutase activity; intramolecular phosphotransferase activity
Biological process: glucose 6-phosphate metabolic process; carbohydrate metabolic process
Cellular component: cytosol
Genetic constraint (gnomAD): Loss-of-function variants: 30 observed, 61.2 expected, observed/expected ratio (o/e) 0.49, 90% interval 0.37 to 0.67. The upper end of that interval is the gene's LOEUF score, 0.67, which puts it in group 2 of 6, group 1 being the genes least tolerant of losing a copy. Missense variants: 544 observed, 715.34 expected, observed/expected ratio (o/e) 0.76, 90% interval 0.71 to 0.82. Synonymous variants: 213 observed, 249.23 expected, observed/expected ratio (o/e) 0.85, 90% interval 0.76 to 0.96.
Homologues: Orthologues: chimpanzee PGM2L1 (99% identical), macaque PGM2L1 (98% identical), rabbit PGM2L1 (96% identical), dog PGM2L1 (96% identical), rat Pgm2l1 (94% identical), guinea pig PGM2L1 (93% identical), mouse Pgm2l1 (93% identical), pig PGM2L1 (92% identical), tropical clawed frog pgm2l1 (77% identical), zebrafish pgm2l1 (71% identical), Caenorhabditis elegans pgm-1 (18% identical), Drosophila melanogaster Pgm1 (17% identical). Paralogues in human: PGM2 (58% identical), PGM1 (19% identical), PGM5 (18% identical), PGM3 (17% identical), HPRT1 (9% identical), PRTFDC1 (8% identical).
Diseases named in the same sentence as PGM2L1 in open-access papers:
PGM2L1 is named in the same sentence as 11 diseases in open-access papers, as found by Europe PMC text mining. Sharing a sentence is not in itself a finding about the gene and the disease. The quoted sentences say what the papers report.
breast carcinoma (2 papers, 2025). "Subsequently, by activating its downstream target phosphoglucomutase 2-like 1 (PGM2L1), CSF3R enhances glycolysis, thereby providing energy to support the malignant phenotype of breast cancer." (PMID 40940764, 2025). "RNA sequencing analysis further revealed that phosphoglucomutase 2-like 1 (PGM2L1) is a downstream target of the CSF3/CSF3R signaling, enhancing the glycolysis pathway and providing energy to support the malignant phenotype of breast cancer." (PMID 40185722, 2025).
gastric cancer (2 papers, 2025). A primary or metastatic malignant neoplasm involving the stomach. "Clinically, high PGM2L1 expression is associated with poorer prognosis in prostate and gastric cancers 21-23." (PMID 40027181, 2025). "Current studies have demonstrated that PGM2L1 is associated with poor prognosis in patients with gastric cancer and prostate cancer." (PMID 40185722, 2025).
neuroblastoma (2 papers, 2018 to 2024). Neuroblastoma (NB) is the most common solid, extracranial childhood tumor. "PGM2L1 and a predicted upstream kinase were overexpressed in a human neuroblastoma cell line and G-1,6-BP levels were measured." (PMID 39182844, 2024). "Remarkably, WMG-2 also had a striking positive correlation (R=0.85, p=9.14 x 10-134) with a published gene set representing genes downregulated in poor prognosis non-MNA neuroblastoma (Asgharzadeh_NB_poor_survival_DOWN), despite only sharing one gene (PGM2L1)." (PMID 29505958, 2018).
prostate carcinoma (2 papers, 2022 to 2025). A carcinoma that arises from epithelial cells of the prostate gland. "A risk score prediction model based on five glycolysis-related genes has also confirmed that PGM2L1 is associated with a poor prognosis in prostate cancer." (PMID 40185722, 2025). "The overexpression of PGM2L1, a glycolysis-related gene, has been reported to be associated with poor prognosis of prostate cancer patients with biochemical recurrence." (PMID 36400759, 2022).
cholangiocarcinoma (1 paper, 2025). A carcinoma that arises from the intrahepatic biliary tree (intrahepatic cholangiocarcinoma) or from the junction, or adjacent to the junction, of the right and left hepatic ducts (hilar cholangiocarcinoma). "To this end, we utilized TIMER, a comprehensive web-based tool, to investigate the association between PGM2L1 expression and immune infiltration levels in cholangiocarcinoma (CCA)." (PMID 40027181, 2025).
lung carcinoma (1 paper, 2021). "To identify novel oncogenes, we focused on 21 downregulated genes that have not been extensively investigated for potential association with lung cancer, including PIF1, GYG2, and PGM2L1." (PMID 34608398, 2021).
Stroke (1 paper, 2024). Sudden impairment of blood flow to a part of the brain due to occlusion or rupture of an artery to the brain. "We further provide evidence that PGM2L1 is important for post-ischemic neuronal survival in an in vitro stroke model and that PMG2L1 activity can be fine-tuned by protein kinases, specifically PKN1." (PMID 39182844, 2024).
tumor (5 papers, 2022 to 2025). "Collectively, these findings suggest that PGM2L1 may serve as an independent prognostic biomarker and is closely linked to tumor immune infiltration and metabolic reprogramming in CCA." (PMID 40027181, 2025). "Our research finds the high expression of PGM2L1 in PAAD is beneficial for promoting tumor malignant progression and glycolysis." (PMID 40507914, 2025). "In cancer cells, PGM2L1 upregulated the level of glycolysis by promoting the conversion from G-1-P to G-6-P, providing energy for tumor progression and metastasis." (PMID 40185722, 2025). "We further investigated the relationship between PGM2L1 expression and tumor-infiltrating immune cells, with a particular focus on neutrophils in CCA." (PMID 40027181, 2025). "Subcutaneous injection was used to generate mouse xenograft tumor models of MIA Paca-2 cells overexpressing PGM2L1, ENO1, co-expressing, and the control into the right dorsolateral regions of these nude mice (n = 4 per group)." (PMID 40507914, 2025). "Taken together, our data verified that CAF-derived CSF3 plays a crucial role in regulating tumor growth and metastasis through PGM2L1 in TNBC." (PMID 40185722, 2025). "A prognostic risk model incorporating NUP37, PGM2L1, and ENO1 effectively predicted patient outcomes, highlighting these genes’ roles in tumor progression." (PMID 40507914, 2025). "This study holds significant potential in advancing our understanding of CCA by elucidating the role of PGM2L1 in tumor progression and immune modulation." (PMID 40027181, 2025). "We implemented it by selecting PGM2L1 expression levels that were negatively correlated with tumor purity." (PMID 40027181, 2025). "Functional validation demonstrated that ENO1/PGM2L1 co-expression promoted tumor proliferation, migration, invasion, and glycolytic flux in vitro, while accelerating xenograft growth in vivo." (PMID 40507914, 2025). "We found that 2-DG significantly abolished PGM2L1-mediated enhancement of TNBC cells proliferation, further confirming that PGM2L1 promoted tumor cell progression through enhanced glycolysis." (PMID 40185722, 2025). "This study is also the first to demonstrate in vitro and in vivo that PGM2L1 regulates EMT under hypoxic conditions, supporting previous evidence that PGM2L1 promotes tumor cell metastasis." (PMID 40185722, 2025). "However, knowledge gaps persist, particularly regarding the precise mechanisms by which PGM2L1 influences the tumor microenvironment and its interaction with immune cells." (PMID 40027181, 2025). "However, the precise mechanisms by which PGM2L1 regulates tumor progression and its potential prognostic value, particularly in CCA, remain unclear." (PMID 40027181, 2025). "However, the reduction in tumor volume observed in sh-CSF3 CAFs groups could be mitigated by the presence of PGM2L1-overexpressing MDA-MB-231 cells." (PMID 40185722, 2025). "Collectively, the data above demonstrated that PGM2L1 enhanced TNBC cells proliferation, migration and invasion by boosting glycolysis and generating more energy, such as ATP, to support tumor progression." (PMID 40185722, 2025). "It was found that CAFs upregulated the PGM2L1 in TNBC cells by secreting CSF3 under hypoxia, and then the enhanced glycolysis in tumor cells promoted progression and adapted to the hypoxic microenvironment." (PMID 40185722, 2025). "The results displayed that growth rates and tumor weights of xenograft tumors in the sh-NC + CSF3 group were higher than in the control group, while the knockdown of PGM2L1 abolished this trend." (PMID 40185722, 2025). "The fluorescence revealed the co-expression of PGM2L1 and HIF-1α in the central region of the tumor, which was considered relatively hypoxic regions." (PMID 40185722, 2025). "Therefore, we identified the methylation site of PGM2L1 in CCA and its prognostic significance, indicating that CCA may utilize distinct methylation sites to modulate tumor development." (PMID 40027181, 2025).
tumor (continued). "Additionally, PGM2L1 appears to regulate key pathways in CCA, including neutrophil infiltration, tumor metabolism, and the Wnt signaling pathway, all of which may contribute to tumor progression." (PMID 40027181, 2025). "Although no inhibitors of PGM2L1 have been discovered, inhibitors of ENO1 have shown good tumor suppression effects." (PMID 40507914, 2025).
cancer (4 papers, 2021 to 2025). A tumor composed of atypical neoplastic, often pleomorphic cells that invade other tissues. "However, despite clinical research data suggesting the potential involvement of PGM2L1 in cancer progression, the underlying molecular mechanisms of PGM2L1 in CCA development remain unclear." (PMID 40027181, 2025). "Importantly, the cancer-promoting effect of PGM2L1 can be partially counteracted by the glycolysis inhibitor 2-DG." (PMID 40185722, 2025). "Consequently, there has been increasing interest in glycolysis-related genes, including PGM2L1, in relation to cancer progression." (PMID 40027181, 2025). "Therefore, PGM2L1 plays a crucial role in glycogen metabolism, glycolysis, and gluconeogenesis as a key enzyme, and increasing evidence links its function to cancer metabolism and progression." (PMID 40027181, 2025).
infection (1 paper, 2017). The state of being infected such as from the introduction of a foreign agent such as serum, vaccine, antigenic substance or organism. "In particular, only a few glycolytic/glucanogenic genes exhibited an infection-induced change in expression (PGM2L1, LDHAL6B, ENO3, ALDH8A1, and ALDH18A1)." (PMID 28993767, 2017). "PGM2L1, ALDH8A1, and ALDHL18A1 on the other hand all displayed a delayed response and were only significantly upregulated by 16 h of infection, while ENO3 exhibited a downregulated response at 16 h." (PMID 28993767, 2017).
neurodevelopmental disorder (1 paper, 2022). A behavioral and cognitive disorder with onset during the developmental period that involves impaired or aberrant development of intellectual, motor, or social functions. "Bi-allelic PGM2L1 mutations are associated with a neurodevelopmental disorder." (PMID 36061364, 2022).